METTL26 (methyltransferase like 26)
Synonyms: JFP2; C16orf13; MGC13114
Tractability: PROTAC: ubiquitination databases record sites on it.
Gene: Protein-coding gene on chromosome 16 (634,412 to 636,378, reverse strand). Ensembl gene ENSG00000130731.
Subcellular location (Human Protein Atlas): Golgi apparatus
Genetic constraint (gnomAD): Loss-of-function variants: 28 observed, 19.26 expected, observed/expected ratio (o/e) 1.45, 90% interval 1.07 to 1.88. The synonymous counts are far from expectation, so gnomAD's model fits this gene poorly and the ratio says little. Missense variants: 344 observed, 222.71 expected, observed/expected ratio (o/e) 1.54, 90% interval 1.41 to 1.69. Synonymous variants: 165 observed, 102.18 expected, observed/expected ratio (o/e) 1.61, 90% interval 1.42 to 1.83.
Homologues: Orthologues: macaque METTL26 (97% identical), pig METTL26 (89% identical), guinea pig METTL26 (88% identical), mouse Mettl26 (86% identical), dog METTL26 (85% identical), rat Mettl26 (83% identical), chimpanzee METTL26 (63% identical), zebrafish mettl26 (58% identical), tropical clawed frog mettl26 (57% identical), Caenorhabditis elegans Y26E6A.3 (43% identical), Drosophila melanogaster CG18661 (43% identical).
Diseases named in the same sentence as METTL26 in open-access papers:
METTL26 is named in the same sentence as 3 diseases in open-access papers, as found by Europe PMC text mining. Sharing a sentence is not in itself a finding about the gene and the disease. The quoted sentences say what the papers report.
cancer (1 paper, 2021). A tumor composed of atypical neoplastic, often pleomorphic cells that invade other tissues. "However, it should be noted that future studies are needed to address the pathophysiological significance and molecular mechanisms of the identified METTLs, such as METTL1, NTMT1, and METTL26, in promoting cancer development and progression." (PMID 34285249, 2021). "In this study, we found that several METTLs, such as METTL2A, METTL2B, and METTL26, which have not been previously investigated systematically, are upregulated at mRNA and protein levels in a subset of human cancers compared to normal tissue." (PMID 34285249, 2021). "We identified a subset of METTL genes, notably METTL1, METTL2A, METTL2B, METTL7B, NTMT1, and METTL26, with high frequencies of genomic amplification and/or up-regulation, while METTL7A and METTL24 were under-expressed, at both mRNA and/or protein levels in a spectrum of human cancers." (PMID 34285249, 2021).
METTL26 also shares sentences with these, for which no sentence is quoted: breast carcinoma (1 paper); tumor (1).